FGF21 (fibroblast growth factor 21)
Diseases named in the same sentence as FGF21 in open-access papers (continued):
Sharing a sentence is not in itself a finding about the gene and the disease.
Mitochondrial myopathy (continued). "FGF21 has been found to be related to OXPHOS dysfunction, as it was induced in a late-onset mitochondrial myopathy mouse model, a transgenic mouse expressing a mutation in the twinkle mtDNA helicase (TWNK)." (PMID 32397676, 2020). "The increased FGF21 secretion observed in the muscles of patients suffering from mitochondrial myopathy was recapitulated in vitro with mitochondrial respiratory chain inhibitors." (PMID 32397676, 2020). "With that purpose, we quantified the steroid hormones, since some steps of their biosynthesis are localized in mitochondria; and FGF21, a recently identified biomarker for mitochondrial myopathies." (PMID 30482867, 2019). "FGF21 can be induced in inguinal fat depots upon cold exposure and in muscle that is under stress induced by a mitochondrial myopathy." (PMID 29107287, 2017). "As muscle tissue is able to express and secrete Fgf21 under conditions of stress, such as in mitochondrial myopathies in humans and in mice, we evaluated the Fgf21 expression in the muscle of simvastatin-treated and control mice." (PMID 27583452, 2016). "In studies of human mitochondrial myopathies, muscle was identified as the source of FGF21 by examining expression of FGF21 in muscle biopsy specimens." (PMID 27832059, 2016). "Fibroblast growth factor-21 (FGF21), a serum cytokine involved in lipid metabolism, has recently been suggested as a potential biomarker for mitochondrial myopathies." (PMID 24116962, 2014). "In a mouse model with mitochondrial myopathy, they found that FGF-21 was induced in muscles and that concentrations in the serum were raised." (PMID 24078096, 2013). "Mice with late-onset mitochondrial myopathy show induction of FGF-21 in their muscles, which is closely related to the number of COX-negative muscle fibres, suggesting that mitochondria deficiency in skeletal muscle induces FGF21 expression." (PMID 23533568, 2013). "Furthermore, FGF21 expression has been significantly increased in the muscles of mice with mitochondrial myopathies, where its levels were directly correlated with the presence of COX-negative fibers, a marker associated with disease severity." (PMID 39882365, 2024). "Notably, FGF21 is considered an established biomarker of human mitochondrial myopathy, and as expected, plasma FGF21 levels were also increased in MERRF patients (8‐fold)." (PMID 37222423, 2023). "Inhibition of mTORC1 with rapamycin was recently demonstrated to slow the progression of mitochondrial myopathy in mouse models by improving several hallmarks of mitochondrial dysfunction, resulting in reduced expression of Atf4, Fgf21, mitochondrial chaperones and key enzymes of the 1C pathway." (PMID 29132502, 2017). "Furthermore, the secretion of FGF21 from human skeletal muscle is strongly induced upon exercise or in pathophysiological conditions including in mitochondrial myopathies and aging, suggesting the involvement of muscle-derived FGF21 in both healthy and pathological conditions." (PMID 35250605, 2022). "Fgf21 could directly or indirectly trigger the pathogenesis of mitochondrial myopathy." (PMID 35906243, 2022). "Since FGF21 is induced in and secreted from skeletal muscle in mitochondrial myopathies and various mitochondrial stressors, it might also act as an adaptive mediator of the muscle mitochondrial stress via activation of pathways that control mitochondrial function." (PMID 33762965, 2021). "Additionally, serum FGF21 is variably increased in non-mitochondrial myopathies." (PMID 32397676, 2020). "Higher “supraphysiological” mitokine levels may, however, either contribute to enhance the underlying abnormalities and via a feedforward mechanism enhance disease pathogenesis or reverse the pathology, as observed in the case of FGF21 in the case of mitochondrial myopathy." (PMID 32691494, 2020). "Deletion of FGF21 appeared to be beneficial in alleviating the disease condition in OPA1 KO mice, a model of mitochondrial myopathy." (PMID 39976232, 2025).
Mitochondrial myopathy (continued). "In particular, patients with confirmed mitochondrial myopathy showed on average the highest GDF-15 levels, and contrary to FGF-21, GDF-15 concentration was ca. 3 times higher in patients presenting with MELAS." (PMID 34203775, 2021). "Thus, FGF21 has recently gained attention as a potential biomarker of mitochondrial diseases and could represent a potential target for the treatment of mitochondrial myopathies and muscle mitochondria dysfunction." (PMID 33762965, 2021). "The specificity of FGF-21 (respectively, GDF-15) to detect patients with mitochondrial myopathy was 89.3% (respectively, 86.4%), and the sensitivity was 67.3% (76.0%, respectively)." (PMID 29385732, 2018). "As both FGF21 and GDF15 are serum proteins that are commonly elevated in mitochondrial myopathies, they may serve as biomarkers of target engagement and treatment responses in IMMD therapeutic trials." (PMID 35700042, 2022). "Altered pyruvate and succinate indicated a metabolic response to mitochondrial dysfunction; however, lactate or mitochondrial myopathy markers FGF-21 or GDF-15 was not changed." (PMID 35250809, 2022). "It is currently not fully understood whether FGF-21 and GDF-15 are altered in mitochondrial diseases predominantly with specific organ involvement (e.g., mitochondrial myopathies) or more generally indicate mitochondrial dysfunction." (PMID 34572118, 2021). "Interestingly, in human patients with mitochondrial myopathy caused by OXPHOS deficiencies, the cytokine, fibroblast growth factor 21 (FGF21), is secreted from muscle tissues, suggesting that OXPHOS dysfunction may mimic fasting and induce the secretion of the fasting-induced hormone, FGF21." (PMID 33165592, 2020). "In MIDs which do not manifest with mitochondrial myopathy, FGF-21 may be normal." (PMID 29385732, 2018). "Previous studies validated both FGF21 and GDF-15 as useful biomarkers in mitochondrial myopathies, even if not highly specific." (PMID 32851462, 2020). "However, elevated FGF21 and GDF-15 in blood have been found also in non-mitochondrial myopathies and, more in general, in non-mitochondrial diseases." (PMID 32851462, 2020).
Hyperinsulinemia (39 papers, 2011 to 2025). An increased concentration of insulin in the blood. "A recent investigation identified that supraphysiological levels of free fatty acids (FFAs) induced by lipid-heparin infusion were associated with elevated serum FGF-21 concentrations, alongside hyperinsulinemia." (PMID 40559404, 2025). "In the present study, OVX increased circulating GCs and caused hyperinsulinemia, while FGF21 LKO completely reversed OVX-induced high GCs and caused hypoinsulinemia in mice." (PMID 37834368, 2023). "Genetic obesity caused hyperinsulinemia in early pregnancy, hyperleptinemia and increased levels of FGF21 in late pregnancy, and reduced weights of placentas, fetuses, and newborns." (PMID 36982684, 2023). "In skeletal muscle, FGF21 is expressed in response to insulin stimulation, suggesting that FGF21 is an insulin-regulated myokine and an association between chronic hyperinsulinemia and levels of FGF21 were found in humans." (PMID 31057418, 2019). "On the other hand, FGF21 deficiency induced islet hyperplasia and hyperinsulinemia as compensatory responses, which were due, at least in part, to the removal of inhibitory effects of FGF21 on islet GH signaling." (PMID 25811804, 2015). "Augmented hepatic PTEN and reduced systemic FGF21 levels, in turn, perturbed hepatic as well as systemic insulin sensitivity, leading to basal hyperinsulinemia and impaired glucose tolerance." (PMID 40311678, 2025). "Previous research has also indicated that obese individuals with hyperinsulinemia have lower FGF21 secretion compared with healthy individuals." (PMID 37755259, 2023). "The reduction of inflammatory markers during hyperinsulinemia are largely in congruency with previous studies, while a stimulative effect has been observed with regard to FGF-21." (PMID 37400734, 2023). "Although the ability of FGF21 to reduce body weight was compromised in Ay mice, FGF21 administration significantly decreased hyperinsulinemia and improved the liver state, but only in males." (PMID 34943946, 2021). "Under lipid heparin infusion–induced supraphysiological level of free fatty acid (FFA), the serum FGF21 level was elevated, accompanied with hyperinsulinemia in a recent study." (PMID 31582974, 2019). "Refeeding (6 h) evoked hyperinsulinemia and increased hepatic expression of gene related to lipogenesis (Fasn) only in males and hyperleptinemia and increase in Fgf21 gene expression in muscles and adipose tissues only in females." (PMID 31783664, 2019). "It has been shown that Fgf21 gene expression is upregulated by hyperinsulinemia in muscle tissue, but refeeding induced muscle Fgf21 expression in females but not in hyperinsulinemic males." (PMID 31783664, 2019). "The results above suggested the protective effects of chronic FGF21 infusion on systemic hyperinsulinemia and excessive sympathoactivation in HFD." (PMID 27387420, 2016). "It is of interest to note that FGF21 administration ameliorated the hyperinsulinemia in the bGH transgenic mice." (PMID 26089880, 2015). "Sex dimorphism in response toFGF21 was reported earlier in obese Ay mice: FGF21 administrationdecreases hyperinsulinemia and hepatic lipid accumulation,increases muscle expression of genes involvedin fatty acid oxidation and insulin signaling only in obeseAy males." (PMID 37469453, 2023). "Overall, these data suggest that FGF19 and FGF21 may have a modulatory role in lipid and insulin metabolism as shown by hyperinsulinemia and the lipid infusion." (PMID 33101202, 2020). "For a long time, the direct targets and mechanisms of blood pressure control by FGF21 actions haven’t been reported, and it may be contributed by its effects on metabolism (hyperinsulinemia) and/or actions on baroreflex and sympathetic nerve." (PMID 27387420, 2016).
Hyperinsulinemia (continued). "Expectedly, in response to FGF21 treatment control littermates showed metabolic improvements whereas GH transgenic mice resisted most of the beneficial effects of FGF21, except an attenuation of the innate hyperinsulinemia." (PMID 26089880, 2015). "However, it is possible that the immune infiltrates may, in part, drive the hyperplasia and hyperinsulinemia observed in the FGF21 KO mice consuming high fat diet." (PMID 26872145, 2016). "Further FGF21-treated bGH mice manifested a near normalization of the hyperinsulinemia, which might explain the greater surge in blood glucose in the Tg-FGF21 group at 15 minutes (P < 0.05), relative to the Tg-vehicle-treated group, upon an exogenous glucose load." (PMID 26089880, 2015). "Lipid and insulin synergistically increased FGF21 in healthy and insulin resistant women with PCOS; hyperinsulinemia suppressed FGF19 in controls." (PMID 33101202, 2020). "Moreover, one study showed that insulin stimulated FGF21 expression during hyperinsulinemic clamp in obese T2DM patients, while the other study demonstrated that acute hyperinsulinemia tended to decrease FGF19 levels in healthy and T2DM subjects." (PMID 24260557, 2013). "Furthermore, we evaluated the beneficial effects of chronic intraperitoneal infusion of recombinant human FGF21 (rhFGF21) on the dysregulated systolic blood pressure, cardiac parameters, baroreflex sensitivity (BRS) and hyperinsulinemia in the high fructose-drinking (HFD) rats." (PMID 27387420, 2016). "Pharmacologic administration of FGF21 imparts resistance to high-fat-diet–induced weight gain, improves glucose tolerance and hepatic and peripheral insulin sensitivity (without triggering hypoglycemia), and normalizes hyperinsulinemia and hypertriglyceridemia." (PMID 33210059, 2020).
hypertriglyceridemia (36 papers, 2015 to 2026). A laboratory test result indicating elevated triglyceride concentration in the blood. "The significant correlation was observed between FGF21 and variables including number of remaining teeth, mean clinical attachment loss, hypertriglyceridemia and low high-density lipoprotein cholesterol." (PMID 36474191, 2022). "Hypertriglyceridemia was associated with markedly decreased serum levels of FGF21, a metabolic regulator with beneficial effects on glucose/lipid metabolism and insulin sensitivity." (PMID 34768942, 2021). "Therefore, it is possible that repression of Fgf21 is the underlying mechanism by which fructose induced hypertriglyceridemia in these rats." (PMID 26458107, 2015). "In a phase 2, randomized clinical trial in patients with severe hypertriglyceridemia, pegozafermin, a long-acting analog of human fibroblast growth factor 21, was safe and met the primary endpoint of the trial for reducing serum triglyceride levels." (PMID 37355760, 2023). "The finding of this study presented that metabolic parameters correlated with FGF21 level were hypertriglyceridemia and low HDL-C, which was in line with the previous reports." (PMID 36474191, 2022). "FGF-21 regulates hepatocyte and adipocyte metabolism, FGF-19 is a regulator of bile acid synthesis (increased bile acid synthesis is seen in hypertriglyceridemia), and FGF-23 has recently been implicated in cardiovascular risk." (PMID 33588820, 2021). "Moreover, dietary protein dilution upregulated the expression of FGF21 and accelerated the oxidative utilization of fatty acids in tissues, thus effectively alleviating hypertriglyceridemia and fatty liver." (PMID 37576954, 2023). "In patients with hypertriglyceridemia, pemafibrate can improve glucose metabolism and liver function, and increase FGF21, without increasing adverse event risk." (PMID 33947390, 2021). "FGF21 is reported to improve insulin sensitivity and hypertriglyceridemia." (PMID 32584895, 2020). "FGF21 also improved the hypertriglyceridemia of Creb3l3−/− mice on KD." (PMID 27301791, 2016). "Clinical studies have suggested that a recombinant FGF21 analog (pegozafermin) can be used to treat nonalcoholic steatohepatitis (NASH) and severe hypertriglyceridemia." (PMID 40141314, 2025). "CREBH also regulates FGF21, which stimulates LPL-mediated TG clearance, thereby contributing to hypertriglyceridemia in CREBH KO mice." (PMID 29738435, 2018). "Similarly, obese patients with mild hypertriglyceridemia had significant improvements in lipid levels and liver fat mass and biomarkers of liver injury with LLF580 (an FGF21 analog) treatment every 4 weeks." (PMID 37576954, 2023). "In addition, FGF21 levels were two times higher in non-diabetic patients with hypertriglyceridemia than in the patients in the control group and were 28% higher during fenofibrate treatment." (PMID 37576954, 2023). "Also, grape seed procyanidin extract, as a strong inducer of Fgf21, could indirectly increase expression of Fgf21 gene and protein by the inhibition of HDAC and subsequent activation of PPARα, thereby, exert therapeutic effect on hypertriglyceridemia." (PMID 34349728, 2021). "With the intake of a high-fructose or high-sucrose diet, Fgf21 and Angptl3, rather than Angptl8, may be better targets for the improvement of hypertriglyceridemia." (PMID 30405056, 2018). "Interestingly, in mice, FGF21 knockdown via short hairpin RNA contributed to hypertriglyceridemia that was not exacerbated by pharmacological inhibition of LPL, suggesting FGF21 may positively regulate peripheral LPL activity." (PMID 35629964, 2022).
hepatocellular carcinoma (35 papers, 2012 to 2025). A malignant tumor that arises from hepatocytes. "Our data also suggests a potential role of FGF21 or other factors released from autophagy-deficient tumors as therapeutic agents in the management of cancer such as hepatoma." (PMID 35321438, 2022). "Furthermore, we revealed the association between plasma Fgf21 and transcriptional changes related to hepatocellular carcinoma (HCC) development." (PMID 27470139, 2016). "About this, higher serum FGF21 levels have been also associated with worse survival in hepatocellular carcinoma (HCC) patients." (PMID 36140410, 2022). "A previous study utilised the dCas9-SunTag and scFv-TET1CD and indicated successful induction of targeted DNA demethylation of the Fgf21 promoter in hepatoma both in vitro and in vivo." (PMID 38473261, 2024). "As a model cell line for in vitro testing of FGF21 mutants’ biological activity, we used the Hep G2 hepatocellular carcinoma cell line." (PMID 38379823, 2024). "FGF21 promotes ferroptosis in hepatocellular carcinoma by upregulating Major vault protein (MVP), which enhances NOX4-mediated ROS production through IRF1 and YAP1 interactions." (PMID 39315094, 2024). "The biological activity of FGF21-WT, FGF21–3PM, and FGF21–4PM was further determined by cell proliferation assay using Hep G2 hepatocellular carcinoma cells and NIH 3T3 fibroblasts." (PMID 38379823, 2024). "Higher blood FGF21 levels were related to worse survival in hepatocellular carcinoma patients, according to a cohort study from Guangdong province." (PMID 37214383, 2023). "The number and size of hepatoma of Atg7ΔHep mice were significantly increased by additional Fgf21 KO." (PMID 35321438, 2022). "Fibroblast growth factor 21 (Fgf21) is one of the target genes of miR-149, which slightly increased intracellular lipid content in a human hepatoma cell line, HepG2 cells." (PMID 36360201, 2022). "Herein, we examined the gene expression and protein levels of FGF21 in human hepatoma HepG2 cells and mouse AML12 hepatocytes in vitro, as well as in mice in vivo." (PMID 35628302, 2022). "Since the increased volume of hepatoma in Atg7ΔHepFgf21−/− mice compared to Atg7ΔHepFgf21+/+ mice suggested increased proliferation of autophagy-deficient tumor due to the absence of FGF21, we next studied whether the proliferation of autophagy-deficient tumor in Atg7ΔHep mice was affected by FGF21." (PMID 35321438, 2022). "Four thousand four hundred seventy-nine potential pathogenic genes (including MYH2, FGF21, and CYP26A1) for hepatocellular carcinoma were integrated, and cointerpretation analysis was performed with a correlated phenotype." (PMID 34651050, 2021). "The SIRT1 activator, resveratrol, increases FGF21 mRNA and FGF21 protein levels in human liver carcinoma HepG2 cells." (PMID 27148532, 2016). "Dibutyryl cAMP was also effective in stimulating FGF21 secretion in the rat hepatoma cell line, H4IIE, and the human hepatoma cell line, HepG2." (PMID 24733293, 2014). "Hepatic ablation of PTEN as a tumor suppressor and the PI3K/AKT signal controller, which resulted in fatty liver and hepatocellular carcinoma, also upregulated FGF21 expression at about 25 times in the PTENf/fAlbCre livers than those of PTENf/f controls." (PMID 23590285, 2013). "FGF21 is also implicated in the development of extrahepatic cancers found more commonly in patients with NAFLD, including breast, colorectal, esophageal, and pancreatic, as well as hepatocellular carcinoma." (PMID 36986211, 2023). "Furthermore, genetic overexpression of Fgf21 has been shown to suppress diethylnitrosamine-induced hepatocellular carcinoma." (PMID 35321438, 2022). "Since FGF21 or other endocrine FGF such as FGF19 can affect tumor growth, we hypothesized that FGF21 produced by Atg7-knockout (KO) hepatocytes may affect the behavior of Atg7-KO hepatoma in an autocrine manner." (PMID 35321438, 2022).